IL6 (interleukin 6)
Diseases named in the same sentence as IL6 in open-access papers (continued):
Sharing a sentence is not in itself a finding about the gene and the disease.
Hepatitis (continued). "Hepatitis-related inflammatory cytokines, such as interleukin-6 (IL-6) and interleukin-1β (IL-1β), have been identified as core promoters of susceptibility to an HBV infection, persistence of an HBV infection, and the initiation, promotion, and progression of the development of HBV-related HCC." (PMID 34451963, 2021). "Furthermore, quantitative RT-PCR indicated a decreased expression of hepatitis-related genes, such as tumor necrosis factor-α, IL-6, and IL-1β in OVX rats after BCE treatment." (PMID 32466275, 2020). "Significantly, higher levels of TNFα, IL-6, and IL-8 were observed in cases of severe hepatitis." (PMID 32124729, 2020). "ARC decreased apoptosis and autophagy in ConA-induced hepatitis might also by the inhibition of IL6/Bnip3 pathway." (PMID 30177931, 2018). "Inhibition of IL-6 signaling has been reported to prevent Con A-induced hepatitis." (PMID 29643811, 2018). "This may mimic events in vivo in which an inflammatory hepatic cytokine microenvironment, found in hepatitis or cancer, dominated by IL‐1, IL‐2, IL‐6, IL‐12, IL‐15, IL‐18, IFNα, IFNγ, and TNFα/β 38, 39, may lead to the expansion of CD49a+ NK cells." (PMID 28952190, 2018). "Thus, it is assumed that TNFα and IL-6 produced by KCs play a significant role in the pathogenesis of the hepatitis." (PMID 28804705, 2017). "On the one hand, IL-6 may promote human Th17 differentiation and IL-17 production contributing to ethanol-induced liver inflammation." (PMID 26107937, 2015). "For example, in a mouse model that mimicked chronic parenteral nutrition use and intestinal injury, liver inflammation was correlated with higher levels of LPS in the portal vein and increased transcription of pro-inflammatory cytokines (IL6, TNF-alpha and TGF-beta) in Kupffer cells." (PMID 24465786, 2014). "Moreover, a specific role for IL-6, together with TNF, has been proposed in the pathogenesis of liver inflammation and cancer associated with dietary and genetic obesity." (PMID 24464501, 2014). "In previous studies, we had shown that liver inflammation induced by T/HS is associated with liver dysfunction and 72% mortality, and IL-6 administration at the start of resuscitation completely reversed T/HS-induced liver inflammation and injury, decreasing mortality 5-fold, to 15%." (PMID 21738667, 2011). "In addition, TACE was linked to an increase in pro-inflammatory cytokines such as IL-6 in the first week following TACE, which was associated with the development of hepatitis, while Th-2 associated cytokines were increased 2 months after TACE, indicating an immune-suppressive environment." (PMID 37012542, 2023). "Interestingly TNF had the highest relevance scores of 75.06, 77.71, 69.39, 95.44, 51.13 for acetaminophen, isoniazid, D-galactosamine, lipopolysaccharide, and rifampicin-induced hepatitis, respectively, and for thioacetamide, IL6 had the highest relevance score of 55.21." (PMID 37446321, 2023). "In addition, IL-17, which is produced by pro-inflammatory T helper 17 (Th17) cells, can promote liver inflammation and fibrosis by facilitating the production of IL-6, IL-1, and TNF-α by inflammatory cells and activating hepatic stellate cells to produce collagen type I." (PMID 36425072, 2022). "Treatment of EpCAM positive tumor patients with catumaxomab caused dose dependent hepatitis as evidenced by significant elevations in serum alanine- and aspartate aminotransferases, bilirubin, γGT and induction of the acute phase C-reactive protein (CRP) and the cytokines IL6 and IL8." (PMID 27058902, 2016). "Although IL-6 has the ability to induce IL-22 production, and IL-6-deficient mice were shown to be highly susceptible to liver damage, these mice were reported to have no impairment in IL-22 expression during Con A-induced hepatitis." (PMID 23956763, 2013). "Thus, our data suggest that AR might mediate the production of TNF-α and IL-6 to influence the development of MCD diet-induced liver inflammation." (PMID 24066058, 2013).
Hepatitis (continued). "Thus the high levels of IL-6 and IL-8 produced by MSC may counterbalance the hepatocyte transplantation-induced liver inflammation caused by pro-inflammatory cytokines produced by Kupffer cells and infiltrating neutrophils." (PMID 22424216, 2012). "Thus, T/HS-induced liver inflammation depends on the duration of hypotension and requires resuscitation; IL-6 administration at the start of resuscitation reverses T/HS-induced liver inflammation, through activation of Stat3α, which normalized the T/HS-induced liver inflammation transcriptome." (PMID 21738667, 2011). "However, due to the lack of a model for CD8+ T cell-mediated chronic hepatitis, whether and how IL-6 plays a role in CTL mediated hepatitis is still unclear." (PMID 21394214, 2011). "The serum IL-1β, IL-6, TNF-α, TBIL, DBIL, ALT, AST and ALP levels decreased with rats treated with PZW where reduced liver inflammation halted its fibrosis and improved overall hepatic health." (PMID 41293246, 2025). "Proinflammatory cytokines released from activated T cells and macrophages, including TNF-α, IFN-γ, IL-6, and CXCL1, are critical in ConA-induced hepatitis." (PMID 40092485, 2025). "Endothelial cells release IL-6, IL-8, and TNF-alpha, which contribute to thrombocytopenia, bleeding, and hepatitis." (PMID 41417343, 2025). "Liver inflammation and fibrosis are regulated by complex immunological pathways, and pro-inflammatory cytokines, such as TNF-α, IL-1 and IL-6." (PMID 40365189, 2025). "SP effectively suppressed IKK, IκB, and p65 phosphorylation, modulated the NF-κB signaling pathway, downregulated IL-1β, IL-6, and TNF-α expression, and mitigated EtOH-induced liver inflammation." (PMID 40362898, 2025). "It appears to either directly or indirectly suppress the expression of pro-inflammatory cytokines such as TNF, IL6, and IL1B, thus alleviating liver inflammation." (PMID 38755697, 2024). "It was shown that IL-6, TNF-α, and s-ICAM-1 concentrations were the highest in patients with hepatitis and biliary pole damage." (PMID 37834802, 2023). "In ConA-induced hepatitis, PI3K-AKT pathway is activated in hepatocytes and dendritic cells, promoting inflammation via inducing the transcription of IL-6 and activation of CD8+ T cell responses, respectively." (PMID 37163367, 2023). "In ConA induced hepatitis mice model, CCN1 conditional knockout (CCN1fl/flCre+) attenuated inflammation by reducing ALT/AST level and IL-6 expression." (PMID 35547732, 2022). "Treatment with MCC950 decreased the serum levels of IL-1β and IL-6, ALT/AST, and the severity of liver inflammation." (PMID 35566282, 2022). "Overproduction of inflammatory cytokines such as IL-1β, IL-18, IL-6, and TNF-α during the activation of IRI-induced immune responses is referred to as liver inflammation." (PMID 35978104, 2022). "Due to the production of a large number of reactive oxygen free radicals, oxidative stress will promote the release of inflammatory factors, such as IL-1β, IL-6 and TNF-α, which leads to liver inflammation." (PMID 34828972, 2021). "An increase in the levels of TNF-α, IL-6, and IFN-γ has been shown to correlate with the disease severity in ConA-induced hepatitis." (PMID 33919375, 2021). "In addition, LPC can protect against hepatitis by binding to type II natural killer T cells, produce anti-inflammatory effects in inflammatory diseases, increase anti-inflammatory factor levels and reduce the production of inflammatory mediators, including interleukin-6 (IL-6) and nitric oxide (NO)." (PMID 34233623, 2021). "Inflammatory factors IL-6, IL-1, and IFN-γ are used as biomarkers of hepatitis in mammals, and their expression has significantly increased in mammalian fatty hepatitis." (PMID 33152216, 2021). "IL-6 is highly upregulated in PLC, which is correlated with rapid progression from hepatitis to PLC." (PMID 32382293, 2020). "The levels of IL-6, TNF-α, and IL-1β in liver macerate supernatants were measured in order to evaluate the early DEN-induced liver inflammation." (PMID 31049358, 2019).
Hepatitis (continued). "In a cyclophosphamide-induced liver inflammation model, rutin downregulated the TNF-α/IL-6 and NFκB/MAPK pathways to protect the liver." (PMID 30781895, 2019). "In addition, WEC was reported to inhibit the elevation of circulating TNF-α and IL-6 levels and ameliorate various chronic inflammatory diseases in animal models, including cotton pellet-induced granuloma and carbon tetrachloride- and γ-irradiation-induced hepatitis." (PMID 31394768, 2019). "It has been reported that AG protects against drug-induced hepatitis by suppressing the immune system and regulating autophagy by inhibiting the IFN-γ/IL-6/Stat1 and IL-6/Bnip3 pathways in mice." (PMID 31163644, 2019). "The pro-inflammatory markers IL-1α, IL-1β, IL-6, TNF, ICAM-1, and VCAM-1 were all significantly upregulated under both hepatitis models." (PMID 29445190, 2018). "The major cytokines involved in hepatitis development are tumor necrosis alpha (TNF-α), interferon gamma (IFN-γ), interleukin-2 (IL-2), and IL-6, of which TNF-α and IFN-γ are the dominant cytokines in irreversible biological damage." (PMID 27035150, 2016). "Recent studies showed that IL-6-/- mice exhibited signs of liver inflammation, and when the IL-6R was deleted only in hepatocytes, mice developed liver inflammation, which could be reduced by Tnf-alpha blockade, suggesting a pivotal balance of IL-6 and Tnf-alpha signalling in the liver." (PMID 27333268, 2016). "Proinflammatory cytokines play important roles in hepatitis, including TNF-α, IFN-γ, IL-2, and IL-6." (PMID 25821351, 2015). "The enhanced hepatitis injury over time was also reflected by the up regulation of serum TNF-α, IL-6, IL-12p70, and IFN-γ, with the peak concentration at the time point of 6 h, followed by a rapid decrease within 48 h." (PMID 24981055, 2014). "To directly view the effect of transferred BM-MDSCs on attenuation of ConA-induced hepatitis in mouse model, we isolated BM from GFP transgenic mice, induced BM-MDSCs with GM-CSF and IL-6, and traced their localization in mice with ConA-induced hepatitis." (PMID 24981055, 2014). "Hepatitis histologic scores (p<0.05); TFA, S100, and CYP2E1 IgG1 antibody levels; and S100 and CYP2E1 IgG2a antibody levels were lower in IL-6−/− mice than in BALB/cBy mice." (PMID 23577207, 2013). "The secretion of these cytokines exhibited a positive correlation among the HIV participants, which aligns with findings from other studies indicating a correlation between the cytokines TNF-α, IL-6, and IL-8 in PLWH coinfected with hepatitis, as well as in individuals with chronic hepatitis." (PMID 41219858, 2025). "The results showed that IL-1β, IL-6, and TNF-α levels were observably increased in the M group, and QJ treatment significantly downregulated this change, which further confirmed that QJ inhibited CCl4-induced liver inflammation." (PMID 38606180, 2024). "Moreover, cynaroside decreased the expression of IL-1β, IL-6 and TNF-α,and inhibited HMGB1 in cecal ligation and puncture-induced liver inflammation." (PMID 38835771, 2024). "Sequentially, CBZ exposure induced liver inflammation in the treated rats; this was evidenced by a significant trigger of NF-κB generation, which can induce the pro-inflammatory biomarkers (TNF-α, and IL-6) to increase in comparison with their levels in the control group." (PMID 37375275, 2023). "Notably, both MSCs and LPS-stimulated MSCs attenuated the production of pro-inflammatory cytokines, such as IL-6 and TNF-α, leading to a reduction in liver inflammation." (PMID 38116551, 2023). "Some hepatic non-immune cells, including endothelial cells and HSC, also have TLRs on their surface that recognize bacterial-specific structural components and subsequently release substantial cytokines such as IL-1, IL-6, and TNF-α, further promoting fibrosis and liver inflammation." (PMID 37872967, 2023).
Hepatitis (continued). "It would be interesting to include an inflammation marker such as plasmatic IL-6 in the new developed model to strengthen its power for hepatitis severity staging a parameter of no less importance." (PMID 35797388, 2022). "we selected four patients who experienced G4 irAEs that lasted >1 week; of these patients, two had skin toxicities and two had hepatitis, results suggested that the changes in CRP, IL-6, and lymphocyte subsets were found to be consistent with the severity of irAEs over time." (PMID 35756643, 2022). "Compelling evidence indicates that utilizing an induced hepatitis model in mice to ameliorate liver damage, as seen by a reduction in inflammatory cytokines Institute for functional nanomaterials (IFN-γ), interleukin-6 (IL-6), interleukin-17 (IL-17), and serum alanine aminotransferase." (PMID 36034890, 2022). "An interesting recent study reported that inhibition of HMGB1/TLR4 intracellular signaling decreased production of NF-κB, TNF-α, and IL-6 in cholestatic liver inflammation, which further confirms the close interactions among HMGB1, TLR4, and NF-κB in the promotion of liver inflammation." (PMID 35335612, 2022). "The mRNA expression of IL-1β, IL-6, TNF-α, TGF-β, α-SMA, Collagen I, Collagen IV, and Fibronectin in the CCl4 group were significantly increased compared with the control group, demonstrated liver inflammation and fibrosis." (PMID 35842576, 2022). "To investigate the anti-inflammatory property of curcuminoids, we determined the expression of common inflammatory markers, such as the toll-like receptors (TLRs) on the surface of innate immune cells, hepatitis cytokines tumor necrosis factor (TNF)-α, and interleukin (IL)-6 in MCD-diet mice." (PMID 35723408, 2022). "Elevated levels of cytokines, including TNF-α, IL-lβ, IL-6, and chemokine monocyte chemoattractant protein-1 (MCP-1) after BDE-47 exposure, induced liver inflammation in mice, aggravated hepatic steatosis and fibrosis in the mouse by oxidative stress and increased pro-inflammatory cytokines." (PMID 33924165, 2021). "In the present work, the antinflammatory capability of Baishouwu extract mainly resulted in decreased levels of MyD88, TRAF6, NF-κB, IL-6 and TNF-α via the reduction of TLR4 expression in hepatitis, cirrhosis, and hepatocarcinoma stages of the HCC models induced by DEN." (PMID 31068809, 2019). "Consequently, curcumin administration induces these PTM regulations of the NF-κB pathway, presumably reducing the production of IL-6 and TNF- α and eventually suppressing hepatitis." (PMID 31717261, 2019). "In order to investigate the induction of cytokines before the peak of LCMV-induced hepatitis, we quantified protein concentrations of chemokine (C-X-C motif) ligand 1 (CXCL1), interleukin 6 (IL-6) and interferon alpha (IFNα) in sera of WT and Trem2−/− mice by ELISA." (PMID 28900132, 2017). "Additionally, IL-2, IL-6, IFN-γ, and TNF-α expression peaked at 12 h, indicating that these cytokines were most robustly expressed during the early phase of ConA-induced hepatitis." (PMID 25821351, 2015). "In addition, IL-2, IL-6, IL-1β and TNF-α were maximally expressed at 6h, indicating these four cytokines mainly expressed in the early phase of Con A-induced hepatitis." (PMID 24498418, 2014). "The role of Stat3 activation downstream of IL-6 in the resistance to T/HS-induced liver inflammation has not been studied previously." (PMID 21738667, 2011). "In the study of peripheral blood mononuclear cells (PBMCs) collected from acute Q fever patients, the production of TNF, IL-6, IL-12, and IL-10 was higher than in control subjects, and TNF and IL-10 levels were higher in patients with hepatitis than in those with isolated fever." (PMID 20594295, 2010). "Moreover, XZTZ pretreatment notably decreased the high levels of pro-inflammatory cytokines induced by alcohol in the liver, including TNFA, IL-6, IL-1B, and MCP-1, indicating that XZTZ could ameliorate alcohol-induced liver inflammation." (PMID 38681193, 2024).
Hepatitis (continued). "In our study, we confirmed that in the group of EBV-infected children without hepatological complications as well as those with hepatitis and concomitant biliary pole damage, the levels of IL-6 and TNF-α were significantly higher than in patients not infected with EBV." (PMID 37834802, 2023). "We found that A. cantoniensis Hance may enhance the activity of protein kinases, promote the growth of neuronal cells body, and regulate hepatitis related signaling pathways (PI3K-AKt, MAPK, IL-2/IL-6/IL-17 signaling pathway and so on), which can serve as a reference in hepatitis E treatment." (PMID 37035802, 2023). "The time courses of four inflammatory mediators, namely IFN-γ, IL-6, IL-10, and TNF-α and the activities of both transaminases, i.e., ALT and AST, in the mice serum were modeled using the newly designed PK/PD/disease progression model of GRMS-55 in ConA-induced hepatitis in mice." (PMID 33919375, 2021). "Activation of STING was associated with an aggravated expression of several inflammatory cytokines, including IL-18, IL-6, IL-1β, TNFα, and C-X-C motif chemokine ligand 10 (CXCL-10) in HFD-induced NAFLD mice, whereas repressing STING signaling attenuated lipid accumulation and liver inflammation." (PMID 33924165, 2021). "Besides LPS-induced peritonitis, similar results were obtained in the ConA-induced hepatitis model, where the treatment with GPI, 6AN or clodronate liposomes inhibited inflammatory cytokines (TNF and IL-6), reduced liver damage, and decreased the mortality rate." (PMID 32286295, 2020). "Most recently, a systematic review and meta-analysis confirmed elevated IL-6 serum levels in HCC patients compared to healthy controls, and showed that HCC patients had even higher IL-6 levels than patients with other chronic liver diseases like cirrhosis or hepatitis." (PMID 31683891, 2019). "TFA-JHDN-5 immunizations induced significantly more hepatitis, serum levels of TFA antibodies, CYP2E1 autoantibodies, and hepatic tissue levels of interleukin (IL)-1β, IL-2, IL-4, IL-5, IL-6, IL-17, interferon (IFN)-γ, and tumor necrosis factor (TNF)-α by 3 weeks." (PMID 30305319, 2018). "IL-6 was also involved in the induction of BNIP3 through the activation of Jak/Stat3 signaling, and the suppression of IL-6/Jaks/Stat3 signaling might contribute to the inhibition of Bnip3-mediated apoptosis and autophagy in ConA-induced hepatitis." (PMID 30177931, 2018). "Con A-induced hepatitis is accompanied by an increase in the serum concentration of several proinflammatory cytokines, including tumor necrosis factor-α (TNF-α), interleukin-6 (IL-6), interferon-γ (IFN-γ) and interleukin-1 (IL-1) which contribute to the development of hepatitis." (PMID 23118999, 2012). "However, the effect of the duration of hypotension on the development of T/HS-induced liver inflammation, as well as the mechanism(s) mediating the protective role of IL-6 administration have not been reported." (PMID 21738667, 2011). "IL-6 has been shown to have a suppressive effect on TNFα and IL-1β production in peripheral blood mononuclear cells and exerts its anti-inflammatory effects in hepatitis by reducing the production of TNF." (PMID 19014513, 2008). "Additionally, the lipid profile and expression levels of Tnf, Il-6, Nf-κb, and iNOS genes decreased, and total SOD and GPx activities significantly increased, indicating that BSE could partially prevent diet-induced oxidative stress and liver inflammation." (PMID 39795230, 2025). "We confirmed a significant decrease in iNOS, COX2, IL-6, IL-1β, and TNF-α in AGF geese, and we found them to be involved in ileal permeability and ileal and liver inflammation in geese lacking pasture supplementation." (PMID 38003191, 2023). "It is of interest that IL-6 is significantly elevated in patients with acute and chronic liver diseases, but its role in CTL-mediated hepatitis has not been defined." (PMID 21394214, 2011).